SATB2 (SATB homeobox 2)
Diseases named in the same sentence as SATB2 in open-access papers (continued):
Sharing a sentence is not in itself a finding about the gene and the disease.
hepatocellular carcinoma (8 papers, 2017 to 2025). A malignant tumor that arises from hepatocytes. "Some proteins, transcription factors such as the erythropoietin-producing hepatocellular carcinoma cell-derived (Eph) family, and special AT-rich sequence binding protein 2 (Satb2) play an essential role during the development of axon projections." (PMID 38338755, 2024). "In hepatocellular carcinoma MIR211 down-regulates SATB2 (Human special AT-rich sequence-binding protein-2) and reduces its invasion and proliferation." (PMID 33628737, 2020). "Hepatocellular carcinoma cells derived from AA expressed the higher level of SATB2 than those from CA." (PMID 31602781, 2019). "Hepatocellular carcinoma cells from AA origin expressed higher levels of SATB2 mRNA and protein and showed aggressive phenotypes than those from CA." (PMID 31602781, 2019). "Similarly, the up‐regulation of SATB2 in hepatocellular carcinoma tissues and cell lines was demonstrated by several groups, suggesting its role was oncogenic." (PMID 32885593, 2020). "However, whether miR-34a can inhibit the proliferation of hepatocellular carcinoma by regulating SATB2 has not been reported." (PMID 30627547, 2018).
lung adenocarcinoma (8 papers, 2013 to 2026). A carcinoma that arises from the lung and is characterized by the presence of malignant glandular epithelial cells. "For instance, hypoxic TDE contains rich miR-31-5p expression and it enhances lung adenocarcinoma metastasis via negatively regulating special AT-rich sequence binding protein-2 (SATB2)-reversed EMT and promoting MEK/ERK signaling pathway." (PMID 38188673, 2023). "CRC lung metastases commonly stain positive for CK20, CDX-2, and SATB2, whereas primary lung adenocarcinomas commonly stain positive for CK7, TIF-1, and napsin A." (PMID 30764882, 2019). "In comparison, SATB2 and CK20 showed higher specificity, with expression in 5% and 10% of mucinous primary lung adenocarcinomas and both in 0% of TTF-1-negative non-mucinous primary lung adenocarcinomas (25–50% and 5–16%, respectively, for GPA33/CDX2/CDH17)." (PMID 37349623, 2024).
lung cancer (8 papers, 2012 to 2024). A malignant neoplasm involving the lung. "Among these genes, six were already identified in the lung cancer related network of genes associated with RETC634Y signature (TMEM45B, CLDN1, TRIM29, SMUG1, SATB2, and EFNA3)." (PMID 38132167, 2023). "During our analysis, increased expressions of PCDH7, DEPDC1B, SATB2, and S100P were detected in lung cancer tissues and adjacent normal tissue of TCGA-LUAD patients, but expression of FGD3 was observed to be lower." (PMID 36530971, 2022). "CircRNA SATB2 participates in lung cancer progression by regulating miR-326/fascin homolog 1 and the actin-bundling protein 1 (FSCN1) loop and is highly expressed in serum exosomes." (PMID 35986010, 2022). "For example, miR-875-5p inhibits the cell invasion by targeting SATB2 in lung cancer." (PMID 32440687, 2020). "Further multivariate Cox regression analyses displayed that SATB2, HLF, and NPAS2 were independently predictive of lung cancer prognosis." (PMID 34925645, 2021). "Collectively, our findings proposed and verified a 3-TF genomic model (SATB2, HLF, and NPAS2) for prediction of lung cancer outcomes." (PMID 34925645, 2021). "In accordance with the regression coefficient derived from multivariate Cox regression models and expression value of SATB2, HLF, and NPAS2, a TF genomic model was conducted for lung cancer prognosis." (PMID 34925645, 2021).
melanoma (8 papers, 2020 to 2025). A malignant, usually aggressive tumor composed of atypical, neoplastic melanocytes. "Overexpression of SATB2, a chromatin remodeler associated with tumor spreading, showed activation of TGFb signaling in early melanomas." (PMID 38874379, 2024). "To gain insight into the mechanism underlying the SATB2-overexpression phenotype in melanoma, we performed ChIP-seq and RNA-seq on primary zebrafish tumors." (PMID 33527896, 2021). "Overexpression of the chromatin remodeler SATB2, which is associated with tumor spreading, shows early activation of TGFb signaling in these melanomas, suggesting that specific melanoma genotypes may benefit from TGFb inhibition." (PMID 38874379, 2024). "Our lab has previously shown that SATB2 overexpression leads to accelerated melanoma onset, produces more aggressive, metastatic tumors, and induces a TGFb signature." (PMID 38874379, 2024). "It is expected that aggressive melanoma subtypes like SATB2, which activate TGFb very early in melanoma development, would be most responsive to early intervention with TGFb inhibitors." (PMID 38874379, 2024). "(C) Dotplot depicting extracellular matrix TGFb target gene expression in TIE:EGFPhigh, TIE:EGFPlow, and TIE:EGFP- SATB2 expressing melanoma cells." (PMID 38874379, 2024). "Of the fish with SATB2 melanomas (n=27), 68% turned on TIE:EGFP in tumors, and its signal was expressed throughout the tumor volume." (PMID 38874379, 2024). "40% of MCR:SATB2 early melanomas (n=27) express TIE:EGFP, compared to 0% of MCR:MCS early melanomas (n=56) (quantification on right)." (PMID 38874379, 2024). "The chromatin remodeler SATB2 is amplified in 4–8% of melanoma patients and its expression correlates with patient outcome." (PMID 38874379, 2024). "Overall, our study shows a robust transcriptional and phenotypic conservation of SATB2 overexpression effects in melanoma across human and zebrafish." (PMID 33527896, 2021). "To validate the effect of SATB2 as a regulator of invadopodia formation in human melanoma, we utilized the panel of iSATB2 human melanoma cell lines." (PMID 33527896, 2021). "Co-localization of F-actin with invadopodium structural component Cortactin in MCR:SATB2 melanoma cell lines confirmed these foci to be invadopodia." (PMID 33527896, 2021). "First, we allotransplanted zebrafish melanoma-derived cell lines Zmel1 (MCR:EGFP) vs. 45–3 (MCR:SATB2) into irradiated casper recipients." (PMID 33527896, 2021). "MCR:SATB2 tumors appear grossly aggressive, are invasive, and melanoma cells are frequently observed in internal organs and spreading along the spinal cord, while organ involvement is rarely observed in MCR:EGFP." (PMID 33527896, 2021). "Upon SATB2 induction, all human melanoma cell lines robustly formed invadopodia and showed significantly increased matrix degradation." (PMID 33527896, 2021). "In summary, we show that melanoma transcriptional rewiring by SATB2 to a neural crest mesenchyme-like program can drive invasion and drug resistance in autochthonous tumors." (PMID 33527896, 2021). "We identify Special AT-rich Binding protein 2 (SATB2) as a novel accelerator of melanoma onset driving an aggressive phenotype in primary tumors suggestive of metastatic spreading." (PMID 33527896, 2021). "(C) Percentage of cells with degraded gelatin after SATB2 induction in iSATB2 human melanoma cell lines A375, SKMEL2, and SKMEL28 transduced with pInducer20-SATB2." (PMID 33527896, 2021). "Overexpression screen of epigenetic regulators identifies SATB2 as an accelerator of melanoma formation in zebrafish." (PMID 33527896, 2021). "Conservation between transcriptional effects induced by SATB2 in zebrafish and human melanoma, and between the SATB2-program and known drug-resistant cell states." (PMID 33527896, 2021).
melanoma (continued). "Through a combination of zebrafish in vivo allotransplants and validation in human melanoma cell lines, we show that SATB2 drives enhanced invasion via invadopodia formation and an EMT-like phenotype." (PMID 33527896, 2021). "(C) Single factor validation of pool F identifies SATB2 to induce accelerated melanoma onset [Median onset 12 weeks, Log-rank (Mantel-Cox) test, p<0.0001****]." (PMID 33527896, 2021). "Through single factor validation of pool F, which had the strongest acceleration phenotype, we identified transcriptional regulator SATB2 as a potent accelerator of melanoma onset in zebrafish." (PMID 33527896, 2021). "(D) Upon SATB2 induction in human melanoma cell line SKMEL2, cells form invadopodia and show increased matrix degradation Scale bar is 20 μm." (PMID 33527896, 2021). "We undertook an overexpression-screen of 80 epigenetic/transcriptional regulators and found neural crest-mesenchyme developmental regulator SATB2 to accelerate aggressive melanoma development." (PMID 33527896, 2021). "We conducted ChIP-seq on MCR:SATB2 primary zebrafish melanomas to identify SATB2-bound target genes." (PMID 33527896, 2021). "In summary, our work identifies SATB2 as a driver of invasion and resistance to Vemurafenib treatment in melanoma." (PMID 33527896, 2021). "Single factor validation of Pool F showed that SATB2-overexpression is sufficient to strongly accelerate melanoma development (median onset of 12 weeks, compared to 21.4 weeks for MCR:EGFP, Log-rank (Mantel-Cox) test p<0.0001****)." (PMID 33527896, 2021). "To determine if there is a change in state of the macrophages that express TIE:EGFP (either endogenously or via phagocytosis), we subset macrophages from the SATB2 expressing melanoma and separated macrophages that were TIE:EGFP+ or TIE:EGFP- based on flow cytometry intensity." (PMID 38874379, 2024). "SATB2 expressing melanomas exhibit TIE:EGFP expression in early initiating lesions." (PMID 38874379, 2024). "It is possible that melanomas up-regulating the epigenetic regulator SATB2 may overcome the tumor-suppressive effects of TGFb signaling earlier in tumor development, leading to more aggressive and invasive melanomas." (PMID 38874379, 2024). "Single cell RNA-seq data from the MCR:SATB2 melanoma suggests that TIE:EGFP+ macrophages (which are either TGFb responsive themselves or had phagocytosed a TGFb responding cell) are not clearly polarized, expressing transcriptional markers of both M1 and M2 states." (PMID 38874379, 2024). "This, in conjunction with down-regulation of interferon by TIE:EGFP+ melanoma cells (as seen in MCR:MCS and MCR:SATB2 tumors), may lead to immune inactivation within the melanoma." (PMID 38874379, 2024). "This shows that overexpression of SATB2 leads to acceleration of TGFb response in melanoma and suggests patients with this amplification may be more susceptible to TGFb inhibitors." (PMID 38874379, 2024). "SATB2 is endogenously expressed in human melanoma at the RNA and protein level." (PMID 33527896, 2021). "To ascertain whether SATB2-induced transcriptional changes were conserved across species, we induced SATB2 overexpression in primary human melanocytes and human melanoma cell lines, and performed qPCR for selected orthologs of genes validated in zebrafish." (PMID 33527896, 2021). "Furthermore, the SATB2-induced transcriptional program shows strong overlaps with known drug-resistance transcriptional states in melanoma." (PMID 33527896, 2021). "qPCR analysis of SATB2 target genes after 48 hr of culture in the presence of doxycycline on iSATB2 melanoma cell lines (SKMEL2, A375, and SKMEL28 iSATB2), and iSATB2 untransformed primary human melanocytes (HEMA-LP) showed a similar increase in SNAI transcription factors." (PMID 33527896, 2021). "Finally, 40% of the MCR:SATB2 fish with melanomas (n=27) had TIE:EGFP expressed in early melanomas." (PMID 38874379, 2024).
melanoma (continued). "Cytoskeletal staining of zebrafish melanoma in vitro cultures (Zmel1 MCR:EGFP and 45–3 MCR:SATB2) with phalloidin revealed the presence of strong F-actin-positive foci in MCR:SATB2 cells, reminiscent of invadopodia." (PMID 33527896, 2021). "(A) Overexpression of SATB2 with TETon (iSATB2) in normal human epidermal melanocytes (HEMA-LP) and in SKMEL2, SKMEL28, and A375 melanoma cells is sufficient to induce transcriptional activation of SOX10, SNAI1/2, PDGFB, and SEMA3F mRNA." (PMID 33527896, 2021). "(F) Isolated melanoma cell clusters were found in the liver, and (G) frequent organ involvement is observed in MCR:SATB2 compared to MCR:EGFP controls." (PMID 33527896, 2021). "To analyze global transcriptional changes induced by SATB2 in human melanoma, we selected SKMEL2 iSATB2, since this cell line had the lowest endogenous SATB2 level and showed the strongest invadopodia induction." (PMID 33527896, 2021). "Using primary zebrafish melanoma in vitro cell cultures, we performed scratch migration assays, that confirmed a heightened migration potential of 3 independent MCR:SATB2 cell lines compared to three independent MCR:EGFP cell lines." (PMID 33527896, 2021). "Our data demonstrate that SATB2-overexpression accelerates melanoma malignant progression without affecting proliferation, but SATB2 is not sufficient and unlikely to be required for melanoma initiation." (PMID 33527896, 2021). "We did not observe proliferation differences between MCR:SATB2 and MCR:EGFP, nor in a panel of three human melanoma cell lines upon inducible overexpression of SATB2." (PMID 33527896, 2021). "To investigate whether in MCR:SATB2 tumors cell fate rewiring functionally induces an EMT-like phenotype-switch reminiscent of the CNC development, we performed whole mount immunofluorescence for EMT markers on primary zebrafish melanomas." (PMID 33527896, 2021). "The acceleration phenotype is not due to increased cellular proliferation, since SATB2-overexpression in primary zebrafish tumors or in a panel of human melanoma cell lines via a TETon tetracycline inducible lentiviral vector (here referred to as iSATB2) did not result in increased proliferation." (PMID 33527896, 2021). "Immunohistochemically, the tumor cells were positive for S100 (5/6), cyclin D1 (2/3), SATB2 (2/3), BCOR (2/4), and TLE1 (1/3) while negative for MUC4 (0/6), keratin (0/5), EMA (0/4), desmin (0/6), CD34 (0/6), SMA (0/5), SOX10 (0/5), and pan melanoma (0/2)." (PMID 40705064, 2025). "Immunohistochemically, the tumor cells were positive for S100 (5/6), cyclin D1 (2/3), SATB2 (2/3), BCOR (2/4), and TLE1 (1/3) while negative for MUC4 (0/6), keratin (0/5), EMA (0/4), desmin (0/6), CD34 (0/6), SMA (0/5), SOX10 (0/5), and melanoma cocktail (0/2)." (PMID 40705064, 2025). "For an unbiased global transcriptional comparison, we conducted RNA-seq on human melanoma NRAS-driven cell line SKMEL2 iSATB2, since it had the strongest invadopodia phenotype, and identified transcriptional differences induced by SATB2 overexpression (with/without Dox induction for 48 hr)." (PMID 33527896, 2021).
metastatic tumors (8 papers, 2012 to 2025). "A recent study showed that the CK7 (KRT7), CK20 (KRT20), and SATB2 immunohistochemical markers could assist in differentiating primary MCs from metastatic tumors." (PMID 36818673, 2022). "However, SATB2 expression has been identified as a useful marker for CRC diagnosis and distinguishing primary colorectal tumors from metastatic tumors, and further research is needed to establish its full clinical utility and potential therapeutic implications." (PMID 37719843, 2023).
mucinous ovarian cancer (7 papers, 2019 to 2025). An invasive malignant neoplasm that arises from the ovary and is characterized by the presence of malignant epithelial cells that contain intracytoplasmic mucin and may resemble the epithelial cells of the endocervix or gastrointestinal tract. "The differential diagnosis of MOC requires a combination of other indicators such as CK7, CK20, CDX2, PAX8, SATB2, and claudin 18.2, which may further reduce the misdiagnosis and missed diagnosis of mucinous ovarian cancer." (PMID 37664708, 2023). "SATB2 is a highly specific marker for gastrointestinal tumors, with no expression in mucinous ovarian carcinoma, making it useful in differential diagnosis." (PMID 39598188, 2024). "In general, the typical primary mucinous ovarian carcinomas are CK7-positive, with diffuse co-expression of CK20 and CDX2, PAX8 and SATB2-negative, while AMNs are CDX2, CK20, and SATB2-positive, and PAX8 and CK7-negative." (PMID 40475008, 2025). "SATB2 is present in individuals with a LAMN and absent in those with a primary mucinous ovarian cancer." (PMID 38672528, 2024). "In addition, new genetic markers are being discovered, such as the Special AT-rich sequence-binding protein 2 (SATB2) marker, which has been found to be positive in those with a LAMN and negative in those with a primary mucinous ovarian carcinoma." (PMID 31901742, 2019).
colorectal tumor (6 papers, 2012 to 2023). "In an immunohistochemical study performed in 146 colorectal tumors, low expression of SATB2 was associated with metastasis development and poor prognosis." (PMID 23121918, 2012). "The lower expression of SATB2 is correlated with the clinical diagnoses and the recurrence rate of the colorectal tumor." (PMID 33166290, 2020). "In summary, our results indicate the existence of a negative feedback loop that maintains low levels of miR-449a and miR-34a as well as high level of SATB2 to promote colorectal tumor development." (PMID 29254139, 2017). "miR-449a overexpression or SATB2 depletion inhibited tumor growth and promoted apoptosis in colorectal tumor cells in vitro and in xenograft mouse model, partially by downregulating SATB2." (PMID 29254139, 2017).
neuroendocrine tumors (6 papers, 2021 to 2025). "From a diagnostic point of view, NECs of our series were completely negative for SATB2, confirming the inconstant expression of this transcription factor in neuroendocrine neoplasms and making SATB2 not useful as a differential marker between grade 4 ONBs and NEC." (PMID 35522392, 2022).